TLR2 (toll like receptor 2)
Diseases named in the same sentence as TLR2 in open-access papers (continued):
Sharing a sentence is not in itself a finding about the gene and the disease.
gastric cancer (continued). "Therefore, the aim of this study was to approximate the importance of TLR2 in the immunopathogenesis of gastric cancer." (PMID 36982898, 2023). "Such complex and multi-level cell signaling in which TLR2 participates, however, requires further comprehensive studies aimed at determining their interaction with selected immune cells and elucidating the pro-cancer mechanisms of gastric cancer." (PMID 36982898, 2023). "Therefore, the results presented by our team are another element indicating the important role of TLR2 in the immunopathogenesis of gastric cancer and its correlation with the stage of the cancer." (PMID 36982898, 2023). "Particularly noteworthy is the role of TLR2 in the pathogenesis of gastric cancer." (PMID 36982898, 2023). "In vitro experiments, we demonstrated that NETs could activate COX-2 through Toll-like receptor 2 (TLR2) and thus enhance the metastatic ability of gastric cancer cells." (PMID 37153547, 2023). "Toll-like receptor 2 (TLR2) was down-regulated in CD8+ T cells of gastric cancer patients, and TLR2 activation could increase the expression of perforin and granzyme B in CD8+ T cells and enhance CD8+ T cells cytotoxicity." (PMID 36341377, 2022). "Above all, TLR2 and its agonists have been proved in many studies to attack gastric cancer cells." (PMID 33469538, 2020). "In addition, we found that a high expression of TLR1, TLR2, TLR4, TLR5, TLR7, and TLR9 associated with an intestinal-type gastric cancer and with a high expression of all other TLRs." (PMID 31467388, 2019). "Therefore, in this study, we aimed to explore the tissue expression of TLR1, TLR2, TLR4, TLR5, TLR7, and TLR9 as potential prognostic biomarkers in gastric cancer patients, and to examine their associations with several clinicopathological variables." (PMID 31467388, 2019). "TLR2 is also involved in the pathogenesis of gastric cancer worldwide." (PMID 30863783, 2019). "Besides other pro-cancer properties, activated STAT3 was shown to stimulate the expression of TLR2 in gastric carcinoma cells." (PMID 29467931, 2018). "Additionally, TLR2 was over-expressed in several human tumour cell lines, such as gastric carcinoma cells and melanoma cells." (PMID 23866094, 2013). "However, studies on cancers other than gastric cancer also indicate the involvement of TLR2 in changes in the tumor microenvironment, enabling its progression, including Goto’s research, in which TLR2 has been shown to be expressed in cells in vivo and in vitro in human melanoma." (PMID 36982898, 2023). "The conclusions drawn by the Xu team suggest that the TLR2 signal may directly regulate the function of CD8 + T lymphocytes, facilitating the pathogenesis and progression of gastric cancer, which is associated with the weakening of the functional functions of CD8 + lymphocytes." (PMID 36982898, 2023). "In gastric endothelial cells, BGN enhances NF-κB binding to the HIF-1α promoter via TLR2 and TLR4 signaling, resulting in increased VEGF expression and enhanced migration of gastric cancer cells." (PMID 41465449, 2025). "On the contrary, TLR2 and TLR5 signal pathways can enhance the proliferation and survival of gastric cancer cells and promote tumor migration." (PMID 38063246, 2023). "Recently, the tissue expressions of TLR1, TLR2, TLR4, TLR5, TLR7 and TLR9 as potential prognostic biomarkers in gastric cancer were reported, showing a positive correlation between each other and a high expression of each studied TLR in tumors with an intestinal-type histology." (PMID 40362298, 2025). "They suggest that TLR2 is a direct transcriptional target of STAT3; additionally, they draw attention to the data of patients with gastric cancer in whom increased activation of the STAT3 pathway, as well as TLR2 expression, negatively affect the survival of the affected person." (PMID 36982898, 2023).
gastric cancer (continued). "Similarly, in the inflammatory microenvironment of gastric cancer, Helicobacter pylori activates downstream inflammatory factors, like IL-6, IL-10, and COX-2, through TLRs (mainly TLR2 and TLR4), thus initiating a series of inflammatory responses." (PMID 37153547, 2023). "Similarly, gastric cells TLR2 responded to NETs and triggered downstream COX-2 release to promote gastric cancer progression." (PMID 37626060, 2023). "In general, our results provide a multi-molecular mechanism by which NETs promote gastric cancer metastasis, emphasize the important role of NETs and COX-2, moreover provide potential targets (NETs, TLR2, COX-2) for the clinical therapy and prophylaxis of the metastasis." (PMID 37153547, 2023). "NETs can promote gastric cancer metastasis by initiating COX-2 through TLR2, and COX-2 may become a target for gastric cancer immunotherapy." (PMID 37153547, 2023). "Furthermore, patient-derived tissue microarrays demonstrated a significant correlation between TLR2 and MnSOD expression in gastric tumours, indicating that the TLR2-MnSOD axis could serve as a potential biomarker for therapy decisions and prognosis determination in gastric cancer." (PMID 36555531, 2022). "Increasing expression of TLR2, TLR4, TLR5, and TLR9 in gastric epithelia of children' gastritis; TLR4, TLR5, and TLR9 in adults' gastritis; TLR2, TLR4, and TLR5 in gastric dysplasia; and TLR4, TLR5, and TLR9 in gastric cancer (GC) is found." (PMID 35300405, 2022). "In contrast, a study of Northern Chinese gastric carcinoma patients found no connection between known polymorphisms in TLR2, 3 and 9 and susceptibility to EBV-associated gastric carcinoma." (PMID 34749760, 2021). "In this study, we found that PUMA is induced by H. pylori by Toll-like receptor 2 (TLR2)/NF-κB-mediated transcriptional regulation and contributes to GEC apoptosis, gastritis, and the progression of gastric cancer, which is significantly attenuated by genetic ablation of PUMA or TLR2." (PMID 32080167, 2020). "Thus, we aimed to evaluate the tissue expressions of TLR1, TLR2, TLR4, TLR5, TLR7, and TLR9 as potential prognostic biomarkers in gastric cancer." (PMID 31467388, 2019). "Conversely, we identified no TLR2 protein expression that functioned as a prognostic biomarker in gastric cancer patients, although the results related to protein expression and gene polymorphism analyses are not directly comparable." (PMID 31467388, 2019). "We additionally confirmed basal expression level of TLR2 and effect of 5-aza-dC in gastric cancer cell lines using qPCR, but TLR2 expression level was not affected by 5-aza-dC except SNU-668 cells." (PMID 26675260, 2016). "In gastric cancer (GC) patient models, compared to healthy volunteers, the expression of TLR-2, TLR-3, TLR-4, and TLR-9 was significantly elevated in GC patients, with higher TLR expression observed in more advanced GC subtypes." (PMID 41488647, 2025). "The literature data on the role of TLR2 in the pathogenesis of gastric cancer are not quite extensive and still require many interdisciplinary studies aimed at determining the cellular mechanisms occurring during the carcinogenesis process in which they are involved." (PMID 36982898, 2023). "In gp130 mutant mice, TLR2 was absent and gastric cancer lesion shrank." (PMID 33469538, 2020). "For instance, TLR2 is overexpressed in more than 50% of human gastric cancers due to the hyperactivation of the STAT3 oncogene that directly induces TLR2 transcription, and increased STAT3 activation and TLR2 expression correlate with poor prognosis in gastric cancer patients." (PMID 33321934, 2020). "Therefore, our study aims to evaluate the expression of Toll-like receptors (TLR-2, TLR-3, TLR-4, and TLR-9) on NK and NKT-like cells in patients with gastric cancer (GC), compare these results with healthy volunteers (HV), and investigate variants depending on the cancer subtype." (PMID 39594809, 2024).
gastric cancer (continued). "In addition to TLR5, TLR1, TLR2, TLR4, TLR7, and TLR9 were also expressed in gastric cancer tissues, yet their expression levels did not function as prognostic biomarkers across the entire patient cohort." (PMID 31467388, 2019).
melanoma (51 papers, 2009 to 2026). A malignant, usually aggressive tumor composed of atypical, neoplastic melanocytes. "High levels of TLR2 expression are positively associated with the overall survival rate in melanoma patients." (PMID 41291775, 2025). "Previously, MIP has shown TLR2/9 mediated activation of antigen presenting cells/Th1 cells and their enhanced infiltration in mouse melanoma but the underlying mechanism by which it is modulating these immune cells is not yet known." (PMID 37122749, 2023). "LASSO regression analysis of melanoma patients identifies TLR2 as a favorable prognostic marker in melanoma." (PMID 40727252, 2025). "Initial contact between melanoma and micro-glial cells is initiated through the recognition of melanoma by micro-glial cells through TLR2/4 and STING pathways, which lead to a transient pro-inflammatory response." (PMID 41463339, 2025). "Upon TLR2‐mediated immune response activation, melanoma cell apoptosis is induced by Th1 and Th2 activation." (PMID 40727252, 2025). "Gram-positive bacteria, such as S. aureus, are recognized by melanoma cells through the toll-like receptor TLR2." (PMID 39284707, 2024). "The forest plot shows that IFNAR2, LBP, CXCL9, and TLR2 are the protective genes for melanoma, while RAC1 and MAPK10 are the risk genes for melanoma." (PMID 37666853, 2023). "Toll-like receptor 2 (TLR2) agonists have been reported to specifically stimulate macrophage antitumor potential after intratumoral injection in melanoma models." (PMID 37457707, 2023). "In a murine melanoma model, it has also been observed that TLR2-activated MCs can recruit NK cells through the secretion of high doses of CCL3." (PMID 37376140, 2023). "It has also been reported that the TLR-2-mediated secretion of IL-6 is responsible for the anti-tumor function of MCs against melanoma and lung cancer, both in vitro and in vivo." (PMID 37376140, 2023). "raised theoretical questions about the study of MALP-2 inhibition in melanoma because the TLR2/6 pathway is expressed not only in immune cells but also in some tumor cells, including B16-F10 melanoma." (PMID 36761746, 2023). "In the B16.F10 mouse melanoma model, the TLR2 agonist Pam3CSK4 induced MCs to release cytokines such as IL-6 and CCL3, which mediated a direct antiproliferative effect on tumor cells and the recruitment of NK and T cells, respectively." (PMID 37376140, 2023). "In a melanoma model, TLR2/6 agonists + IFN-γ can induce CXCL10 production, leading to more T cells migrating into TME." (PMID 35818037, 2022). "B16 melanoma cells that express MMP2 at baseline have slower kinetics in Tlr2–/–Tlr4–/– mice, implicating MMP2 in promoting tumor growth." (PMID 34032639, 2021). "To further assess the possibility that the combination of a TLR2 agonist and GM-CSF protects against metastatic cancer, we used a melanoma lung metastasis mouse model." (PMID 34599024, 2021). "MMP2 expression in melanoma promotes tumor growth in a TLR2- and TLR4-dependent manner that requires APCs and T cells." (PMID 34032639, 2021). "Regarding the activation of extracellular TLRs, Diprovocim, a small drug agonist of TLR2, identified through a screening of molecules on macrophages, showed efficacy in combination with anti-PD-L1 antibodies in a melanoma model." (PMID 33050070, 2020). "The expression levels of Clec7a and Tlr2 were increased in mice treated with T. stromaticum and inoculated with murine melanoma compared to controls only inoculated with melanoma." (PMID 32547964, 2020). "A similar antitumoral activity, mediated by TLR2 activation, was observed for the intratumoral injection of a modified glucomannan polysaccharide in murine models of sarcoma and melanoma." (PMID 33050070, 2020). "The efficacy of TLR2 stimulation on tumor-infiltrated leukocytes was demonstrated also in a melanoma model." (PMID 33321934, 2020).
melanoma (continued). "In the current study the effect of Zymosan A derived from Saccharomyces cerevisiae on serum TNF-α expression and on TLR2 and 4 genes expression in peritoneal macrophages and on melanoma growth progression was investigated." (PMID 29588627, 2018). "In contrast, zymosan significantly induced TNF-α and TLR-2 mRNA expression in both healthy (Z) animals and in melanoma-bearing (ZM) animals." (PMID 29588627, 2018). "Melanoma growth was associated with a significant reduction in TNF-α, TLR-2 and TLR-4 mRNA expression in peritoneal macrophages compared to that in control mice (P < 0.05)." (PMID 29588627, 2018). "A recent study demonstrated that the TLR2/6 agonist MALP-2 prevents the metastasis of melanoma to the lungs." (PMID 28212561, 2017). "Due to the fact that IL-6 mRNA levels remained unaffected in our study we believe that the mechanism behind WNT5A induced IL-6 release in malignant melanoma cells is Myd88/TLR2 independent." (PMID 24766647, 2014). "Cancer cells from other sites (e.g., melanoma, breast) have been shown to express TLR2, and TLR4 expression has been noted on tumour cells in head and neck squamous cell carcinoma." (PMID 21179035, 2011). "In THP-1 cells, the dominant signaling pathway of melanoma cell-derived TEX involves HSP-90/TLR2." (PMID 41595119, 2026). "Inhibition of Tlr2 has been shown to reduce pulmonary metastases in melanoma." (PMID 40458726, 2025). "Additionally, studies indicate that tumor-derived TLR2 ligands, stimulating TLR2+ DCs, impair the activity of DCs in mice melanoma." (PMID 38057843, 2023). "Moreover, the interaction of TLR2, TLR3 and TLR4 with their ligands on human melanoma cells was associated with increased cell migration and tumour metastasis." (PMID 33336901, 2021). "For example, the combination of an anti-TLR2 monoclonal antibody with the cytotoxic agent gemcitabine synergistically inhibited the development of pulmonary metastases in a preclinical model of mouse melanoma." (PMID 33321934, 2020). "The variant allele for TLR2-rs3804099 was associated with an increased risk (OR = 1.15, 95% CI 0.99–1.34, p = 0.07) and for TLR4-rs2149356 with a decreased risk (OR = 0.85, 95% CI 0.73–1.00, p = 0.06) of melanoma." (PMID 21931695, 2011). "Besides, TLR2 is also a treatment target of melanoma metastasis." (PMID 37153547, 2023). "Clear PSME2 and TLR2 co-expression was evident in COAD, GBM, LIHC, PAAD, osteosarcoma, and melanoma." (PMID 38385075, 2024). "By integrating a series of bioinformatics methods, our study identified 6 TLR-related genes (IFNAR2, RAC1, LBP, TLR2, MAPK10, CXCL9), which have the potential to serve as new indicators of melanoma progression and prognosis." (PMID 37666853, 2023). "STAT1 and IL-32 signaling mediates immunoresponse upon TLR2/6 agonists and IFN-gamma treatment in melanoma." (PMID 31024232, 2019). "TNF-α mRNA expression in melanoma-bearing mice (M) was reduced by 83% compared to control mice while TLR-4 and TLR-2 mRNA expression was suppressed by 70% and 35%, respectively compared to control mice." (PMID 29588627, 2018). "Distribution of the most common haplotypes within TLR2, TLR3 and TLR4 in German melanoma patients and German controls." (PMID 21931695, 2011). "In clinical settings, TLR2 inhibitors are being investigated in combination regimens, enhancing the efficacy of chemotherapy, anti-angiogenic agents (e.g., bevacizumab), and immunotherapies, showing synergy with TLR9 agonists (CpG ODN) in melanoma models." (PMID 41375047, 2025). "Spatial transcriptomic data from Spatial DB further confirmed that PSME2 expression patterns overlapped substantially with those of the macrophage marker CD68 and the M1 macrophage marker TLR2 in BRCA and melanoma, implied potential co-localization of these genes." (PMID 38385075, 2024).
melanoma (continued). "Subsequently, employing a similar approach, we conducted a thorough analysis of the correlation between the clinical characteristics of melanoma and remaining five model genes, i.e. IFNAR2, LBP, MAPK10, RAC1, and TLR2." (PMID 37666853, 2023). "Indeed, TLR2 signalling plays an important role in the BCG-based treatment of bladder cancer and in-transit melanoma." (PMID 36499361, 2022). "Similarly, a derivative of Escherichia coli lipid A, OM-174 (CXR-526), engaging both TLR2 and TLR4, is being tested in a phase I trial against a solid tumor and phase I/II trials as a vaccine adjuvant for melanoma treatment." (PMID 32012718, 2020). "Furthermore, we established a subcutaneous B16-F10 melanoma model for intratumoral BCG treatment and compared wild type mice to TLR2-/-, TLR3-/-, TLR4-/-, TLR7-/-, TLR3/7/9-/-, caspase 1-/-, caspase 11-/-, IL-1R-/-, cGAS-/-, STING-/-, IFNAR-/-, MyD88-/-deficient animals." (PMID 38835781, 2024). "The importance of T-cell–mediated TLR signaling is emphasized by reversed or delayed tumor growth of B16 melanoma in tumor-bearing MyD88 knockout mice that received adoptive transfer of TCR-transgenic CD8+ pmel T cells, after peritumoral injections of Pam3CSK4 (a synthetic TLR2 agonist)." (PMID 32012718, 2020). "A hint toward this hypothesis is conferred by the observation that a vaccine constituted by irradiated B16 melanoma cells engineered to express GM-CSF suppressed tumor growth in TLR2−/− but not in wild-type mice." (PMID 33321934, 2020). "However, our concept is unique, because of the specific combination of TLR ligands (particularly TLR2, TLR3, and TLR7/8), which seems to have an extraordinary effect on innate immunity activation and tumor elimination, as previously presented in melanoma and pancreatic adenocarcinoma mouse models." (PMID 31083581, 2019). "Our study suggests that zymosan-induced upregulation of TLR-2, TLR-4 and TNF-α gene expression and of TNF-α release; together with increased level of lymphocyte proliferation may play a role in the inhibition of melanoma progression." (PMID 29588627, 2018). "In melanoma, TLR5 is not as well studied as TLR2 or TLR4, but evidence suggests that many cell lines express TLR5 to varying degrees, and therefore, innate and adaptive immunity could be activated by TPV/Δ2L/Δ66R/FliC infections in melanoma cells." (PMID 37628585, 2023).